EZH2 (enhancer of zeste 2 polycomb repressive complex 2 subunit)
Diseases named in the same sentence as EZH2 in open-access papers (continued):
Sharing a sentence is not in itself a finding about the gene and the disease.
tumor (continued). "Collectively, these data suggest E2F7 is involved with multiple oncogenic process and a potentially key regulator of EZH2 transcriptional activity in HGG tumor cells." (PMID 32064771, 2020). "The expression of EZH2 was coincidentally also found to be overexpressing in tumor tissue in the same datasets considered earlier." (PMID 32943993, 2020). "Our results show, for the first time, that the under-expression of miR-33b is related to the poor prognosis and low survival in HER2+ BC, while a high expression of EZH2 is directly proportional to tumor aggressiveness and proliferation." (PMID 33014831, 2020). "Leveraging these findings into improved treatments will clearly require distinct plans depending on the tumor type and the predominance of either EZH2 or the KDM6 proteins in supporting tumor growth." (PMID 33003334, 2020). "On the other hand, inactivation of Ezh2 accelerates tumor initiation in a mouse model of Group 3 MB induced by Gfi1 and c-Myc, suggesting a different role for these players in different subset of MB26." (PMID 31996670, 2020). "Both physical and fluorescence imaging results exhibited that silencing EZH2 by lentivirus significantly inhibited tumor size in nude mice." (PMID 33363140, 2020). "This is the most direct evidence proving that tumor metabolism affects the enzymatic activity of EZH2 via post-translational modification (PTM)." (PMID 32448308, 2020). "As a core member of the Polycomb group (PcG) protein family, EZH2 plays an important role in stem cell maintenance and tumor development and is overexpressed in various cancers." (PMID 33163485, 2020). "In particular, they showed that EZH2 is upregulated upon anti-CTLA-4 or IL-2 immunotherapies in cancer cells, leading to a loss of tumor control." (PMID 32042336, 2020). "The indispensable role of H3K27me3 in EZH2-mediated repression of genes in tumorigenesis and tumor progression has also been documented, while expression of H3K27me3 and EZH2 are indicative of poor prognosis of patients with ESCC." (PMID 33330444, 2020). "Further clinical studies revealed that high expression of EZH2 stratified the HCC patients into those with elevated neoplasm disease stage, enhanced cancer progression, and high histologic grade." (PMID 33168810, 2020). "As a crucial epigenetic regulator of gene expression, EZH2 is functionally involved in many aspects of multiple carcinomas, such as tumor initiation, tumor cell survival, chemoresistance, invasiveness, metastasis, and angiogenesis." (PMID 32635336, 2020). "Taken together, these findings highlight that EZH2 can function as a tumor suppressor and oncogene depending on the cellular context." (PMID 32650416, 2020). "Co-administration of EZH2 inhibitors (GSK343 or DZNep) with gefitinib exerted a stronger inhibitory effect on tumor activity, cell proliferation and cell migration than single drug administration in vitro and in vivo." (PMID 33276757, 2020). "In this tumor type, a mutation in the SET domain of EZH2 (Tyr641) was present in 21.7% of diffuse large B-cell lymphoma and 7.2% of follicular lymphomas of the germinal-center origin." (PMID 32182803, 2020). "In the subcutaneous tumour model, E2F7 silencing had significantly inhibited tumour growth compared with control groups, and this effect was rescued by the EZH2 overexpression." (PMID 32814835, 2020). "In this study, we determined the differences in EZH2 expression levels between paired tumor and paracancerous lung tissues using the TCGA database." (PMID 33276757, 2020). "In support of such strategies, EZH2 inhibitors reduce tumor progression and synergize with anti-CTLA4 therapy in a T-cell-dependent fashion." (PMID 33143070, 2020). "EZH2 silence appreciably attenuated the metastatic tumor burdens in liver, while re-expression with EZH2 conspicuously increased the burdens." (PMID 32127003, 2020). "EZH2 regulates the proliferation and survival of tumor PC by inducing the expression of genes that promote PB proliferation." (PMID 33126754, 2020).
tumor (continued). "In a wide variety of cancers, including GBM, EZH2 is highly expressed, and its expression is positively correlated with tumor malignancy and invasiveness." (PMID 32410622, 2020). "3-Deazaneplanocin A (DZNep) is an indirect inhibitor of EZH2 currently in the pre-clinical phase of drug development and has been shown to promote apoptosis in various primary tumor cells and cancer cell lines." (PMID 32408898, 2020). "Recent studies identified EZH2 as a non‐canonical RNA‐binding protein that is a key regulator in the development of tumours." (PMID 32885590, 2020). "In several tumor models, the knockdown of EZH2 protein expression results in proliferation inhibition, further demonstrating that EZH2 is a bona fide oncogene." (PMID 33163485, 2020). "Our collective results support the utility of combination therapy involving EZH2 inhibition and pomalidomide for EZH2-mutated DLBCL and provide insights into the mechanisms underlying tumor suppression activity." (PMID 32906688, 2020). "EZH2 dysregulation is highly tumorigenic and has been observed in various cancers, with EZH2 acting as an oncogene or a tumor-suppressor depending on cellular context." (PMID 32650416, 2020). "Functionally, DDX11 promoted cell proliferation by inducing the expression of EZH2, a famous oncogene, to subsequently inhibit the expression of p21, a well-known tumor suppressor." (PMID 33614480, 2020). "Ezh2 inhibition blocked OM-induced cancer cells growth, DZNep reduced the size of the ex vivo cultures of OM-derived tumor spheroids." (PMID 31996670, 2020). "In SCCOHT it was shown that EZH2 inhibitors induced cell cycle arrest, apoptosis and cell differentiation in tumor cells as well as suppression of tumor growth and improved survival in murine models." (PMID 33230143, 2020). "Both cell lines overexpressed EZH2 and other members of the polycomb repressive complex and EZH2 inhibition in RMC tumor spheroids resulted in decreased viability." (PMID 32259323, 2020). "EZH2 inhibition can enhance tumor immunogenicity through activation of endogenous retroviruses and can modulate immune cell differentiation." (PMID 32041674, 2020). "Both oncogenic, as well as tumor-suppressive lncRNA species are connected to EZH2 via different mechanisms." (PMID 32331331, 2020). "Ezh2 is negatively affected by factors present in the tumor microenvironment (TME) as evidenced by the reduction of Ezh2 transcription when T cells were activated in the presence of lyophilized tumor supernatant." (PMID 33117406, 2020). "EZH2 inhibitors can enhance the sensitivity of tumor cells to antitumor drugs and thereby enhance the efficacy of the drugs." (PMID 33276757, 2020). "Here, we established that high EZH2 expression correlated with enhanced tumor size, elevated metastasis, increased relapse, and poor prognosis in HCC patients." (PMID 33168810, 2020). "EZH2 overexpression is frequently detected in HCC, and the mechanisms by which EZH2 promotes HCC are associated with tumor growth and metastasis." (PMID 33207561, 2020). "For instance, EZH2 can promote the invasion and metastasis by suppressing E-cadherin transcriptional expression; EZH2 can also increase tumorigenesis by silencing tumor suppressors." (PMID 33308321, 2020). "E2F1, which binds to the EZH2 promoter and induces its expression, is enriched in the nucleus of tumor PC due to the abnormally high basal activity of the PI3K/Akt pathway in MM." (PMID 33126754, 2020). "With the exception of its role in tumor growth, EZH2 also participates in the metastasis of cancers." (PMID 33046994, 2020). "Enhancer of zeste homolog 2 (EZH2) is considered an important driver of tumor development and progression by its histone modifying capabilities." (PMID 32408898, 2020). "The histological analysis of retinal detachment due to tumor growth showing high level of H3K27me3 supports also a potential role for EZH2 in photoreceptor death, in pathophysiological conditions in situ." (PMID 33324144, 2020).
tumor (continued). "With a dual tumor suppressive and oncogenic role of EZH2, caution is warranted when modulating PRC2 function, and thus, H3K27 methylation in therapeutic strategies." (PMID 32650416, 2020). "On a molecular level, p16 and PTEN, two well-known tumor suppressors, were shown to be negatively regulated by EZH2." (PMID 32331331, 2020). "Histone methyltransferase EZH2 is overexpressed in various malignant tumors and involved in promoting tumor growth and metastasis." (PMID 32370249, 2020). "The “writer” of H3K27me3, enhancer of zeste 2 (EZH2), has been known to be involved in tumor progression in an oncogenic capacity for over twenty years." (PMID 33003334, 2020). "Next, we investigated the impact of CRNDE on several tumor suppressor genes that are reported to be inhibited by EZH2, SUZ12, and SUV39H1-mediated histone trimethylation." (PMID 32826865, 2020). "MAK683, the embryonic ectoderm development protein (EED) inhibitor, can induce reduced tumor cell proliferation in EZH2 mutated cells through binding to EED to block the interaction between EED and EZH2." (PMID 33317571, 2020). "Overexpressing ZMYND8 transcriptionally represses the expression of drug resistance, stemness, and tumor-promoting genes by repressing their poised promoters in association with KDM5C and EZH2." (PMID 33323928, 2020). "In human and mouse HNSCC, EZH2 inhibitor or CRISPR-mediated EZH2 deficiency enhanced MHC-I expression and antigen presentation on tumor cells, and increased antigen-specific CD8+ T cell proliferation, IFN-γ production, and tumor cell cytotoxicity." (PMID 33344447, 2020). "We also found that the co-administration of EZH2 inhibitors with gefitinib exerted good tumor-suppressing effects against primary gefitinib-resistant cells in vivo." (PMID 33276757, 2020). "PRC2 is recognized as important and context-dependent tumor suppressive or oncogenic molecule, and its subunits EZH2 and SUZ12 were reported to inhibit the the expression of numerous tumor suppressor genes by influencing H3K9me and H3K27me3 levels." (PMID 32826865, 2020). "In contrast, loss-of-function mutations in PRC genes, such as EZH2, EED, SUZ12, BCOR, and BCORL1, have been found in various hematological malignancies, suggesting their tumor suppressor functions." (PMID 33374737, 2020). "EZH2 inhibition also was shown to enhance tumor immunogenicity through increased interferon signaling, production of proinflammatory chemokines CXCL9 and CXCL10, and modulation of immune cell differentiation." (PMID 32182803, 2020). "Studies in mice xenografted with human MM cell lines (HMCLs) have shown that EZH2 is an oncogene in MM and that its pharmacological inhibition has an anti-tumor effect." (PMID 33126754, 2020). "The higher the expression level of EZH2, the higher the malignant degree of tumor and the worse the prognosis." (PMID 33194612, 2020). "Here, our data show that HNF1B directly represses SLUG in mediating its tumor suppressive role and establish a molecular link between EZH2 and EMT process." (PMID 31636385, 2020). "Since the response to EZH2 inhibitors correlates with EZH2 overexpression, we then investigated protein expression of EZH2 by IHC staining in tumor cells of Ov-CCA." (PMID 33344089, 2020). "Studies have found that EZH2 is closely related to tumor proliferation, metastasis and poor prognosis." (PMID 33194612, 2020). "In epithelial OCs EZH2 is also often overexpressed and thereby promotes proliferation and invasion of tumor cells." (PMID 33230143, 2020). "ChIP‐sequencing data from ENCODE (Encyclopedia of DNA Elements) revealed clear binding peaks for E2F7 at promoter area of EZH2 in K562 tumor cells." (PMID 32064771, 2020). "Herein, we demonstrate that combination of GSK126 with pomalidomide synergistically inhibit tumor growth through inducing B-cell maturation and apoptosis in EZH2 gain-of-function mutant DLBCL." (PMID 32906688, 2020).
tumor (continued). "In this review, we have summarized the correlation between EZH2 and cellular metabolic activity during tumor progression and drug treatment." (PMID 32448308, 2020). "Via qRT‐PCR, we found that silencing of E2F7 induced significant reduction of EZH2 mRNA expression in U87 and U373 tumor cells." (PMID 32064771, 2020). "This suggests that EZH2 directly represses (via H3K27me3) several tumor suppressor genes and genes involved in differentiation, and indirectly activates oncogenes." (PMID 33126754, 2020). "Chromatin immunoprecipitation (ChIP) assay identified that HEIH increased binding of EZH2 and levels of H3K27me3 across p16 promoter resulting in silencing of this tumor suppressor." (PMID 32429062, 2020). "These previous studies indicated that overexpression of EZH2 modulates epigenetic silencing of genes involved in tumor progression." (PMID 33180829, 2020). "Inhibition of EZH2 activity can stimulate the expression of tumor suppressor genes, thus inhibiting tumor cell growth." (PMID 33344447, 2020). "Meanwhile, the stability and methyltransferase activity of EZH2 can be also affected by the metabolic activity of tumor cells through various mechanisms, including post-translational modification." (PMID 32448308, 2020). "Taken together, our results expanded our knowledge of the regulatory network between E2Fs and EZH2 in AML and confirmed that E2F4 functions as a tumour suppressor in AML via inhibition of the MAPK signalling pathway by binding to EZH2." (PMID 31943751, 2020). "We comprehensively examined the expression of EZH2, its correlation with prognosis, and the status of different tumor-infiltrating immune cells based on data from patients with HCC in The Cancer Genome Atlas (TCGA) and various public databases." (PMID 33180829, 2020). "Matrix‐metalloproteinases (MMPs) (MMP2 and MMP9), closely related to the tumor cell metastasis, were downregulated by EZH2 knockdown." (PMID 31855281, 2020). "Genetic loss of EZH2 leads to a more advanced MPN phenotype and decreased survival in MPN mouse models, suggesting EZH2 plays a tumor suppressive role in MPNs." (PMID 33329600, 2020). "Given the important role of EZH2 in tumor pathogenesis, developing small molecule inhibitors of EZH2 becomes popular and clinical trials are underway to test these molecules." (PMID 33665162, 2020). "Tumor angiogenesis plays an important role in tumor metastasis, EZH2 is also a key regulator of this process." (PMID 32723346, 2020). "EZH2 plays a key role for the function of tumor-specific effector T cells, while tumor microenvironments reduce EZH2 expression of T cells via glucose restriction and in turn, mediates T cell dysfunction." (PMID 32723346, 2020). "In summary, it can be stated that EZH2 can promote glucose metabolism in tumor cells, thus maintaining and promoting their high energy demands and survival, respectively." (PMID 32448308, 2020). "It functions as a tumor suppressor and several therapeutic targets in ARID1A-mutated cancers are currently under development, including EZH2." (PMID 33344089, 2020). "Probably it can be an indirect tumour aggressiveness inhibitory effects through targeting EZH2 in the specific BC subtype." (PMID 33014831, 2020). "EZH2 (enhancer of zeste homolog 2) regulates epigenetic gene silencing and functions as critical regulators in various tumor progression." (PMID 31855281, 2020). "In ovarian cancer, cancer cells limit glucose metabolism by reducing the expression of T cell methyltransferase EZH2, thereby inhibiting T cell function and ultimately promoting tumor progression." (PMID 34766109, 2020). "EZH2 can also epigenetically repress tumor suppressor mRNAs or miRNAs to promote tumor proliferation." (PMID 33163485, 2020).
tumor (continued). "The co-administration of these EZH2 inhibitors with gefitinib exerted stronger inhibitory effects on tumor activity than the administration of either drug alone." (PMID 33276757, 2020). "The emerging studies have explored that EZH2 is involved in altering the metabolic profiles of tumor cells by multiple pathways, which cover glucose, lipid, and amino acid metabolism." (PMID 32448308, 2020). "While many researches have revealed oncogenic roles of EZH2, the tumor-suppressive roles are also reported." (PMID 32723346, 2020). "O-GlcNAcylated EZH2 have downregulated the epithelial cell markers claudin-7 and E-cadherin and enhanced tumor migration and invasion, leading to the metastasis of advanced colorectal cancer (CRC)." (PMID 32448308, 2020). "The expression of EZH2 and the correlation between the high expression of EZH2 and cancer stage between normal specimens and tumor specimens were compared." (PMID 33299862, 2020). "Taken together, these results indicate that E2F4 functions as a tumour suppressor in AML via inhibition of the MAPK signalling pathway by binding to EZH2." (PMID 31943751, 2020). "EZH2-mediated PRC2 activation contributes to the transcriptional silencing of tumor suppressor genes, leading to the activation of NOTCH, JAK-STAT, or β-catenin signaling pathways and upregulation of cell cycle genes, such as CDK2, CDK4, and CCND1." (PMID 33121524, 2020). "The enhancer of zeste homolog 2 (EZH2) plays a critical role in different components of anti-tumor immunity." (PMID 33180829, 2020). "In Patient #3, refractoriness to different treatment regimens was associated with persisting metabolically active tumor areas seen on the PET-CT scans and synchronously high VAF of EZH2 mutated ctDNA was detected." (PMID 32668764, 2020). "EZH2 is a factor that can counteract the tumour‐suppressive qualities of KLF2 by binding to its promoter region, silencing KLF2 transcription." (PMID 32420685, 2020). "This study further identified EZH2 as an independent dismal predictor for overall survival, after accounting for known prognostic factors, such as age, race, tumor type, lymphovascular invasion, tumor grade, and clinical FIGO stage." (PMID 33050946, 2020). "It was demonstrated that EZH2 epigenetically silences many tumor suppressor miRNAs, including miR-101, in human HCC cells, such as SMMC-7721, MHHCC97L and HepG2." (PMID 32429062, 2020). "EZH2 inhibitors and prednisolone were shown to have synergistic anti-tumor activity in a DLBCL mouse model." (PMID 33374737, 2020). "Herein, the protein and mRNA expression of EZH2 were found significantly higher in HCC tissues, and mRNA expression of EZH2 was highly correlated with tumor grades and prognosis of HCC patients." (PMID 33575212, 2020). "As chronic pancreatic injury is associated with high neoplastic risk, loss of EZH2 promotes neoplastic progression, which is also demonstrated by the mice experiment that loss of EHZ2 accelerates KRasG12D-driven neoplasia." (PMID 32723346, 2020). "Tumor-suppressive miRNAs that directly target EZH2 to inhibit TNBC progression include miR-1301 and miR-340." (PMID 32206036, 2020). "HOXB13 can directly upregulate a series of genes related to metastasis and drug resistance by directly binding to EZH2, promoting tumor progression and predicting poor prognosis." (PMID 33299862, 2020). "EZH2 plays a controversial role in cancer development, acting as either an oncogene or a tumor suppressor depending on the type of cancer." (PMID 32066746, 2020). "Destabilization of Treg cells by a deficiency of critical Treg-associated factors such as Nrp-1, SOCS1, EZH2, Eos or CARMA1 protects hosts from syngeneic tumor growth." (PMID 33024109, 2020). "This is further emphasized by the reactivation of the CLU gene by all the G9a inhibitors shown in our studies, as it is a NB tumor suppressor gene known to be regulated by EZH2 and MYCN." (PMID 32537432, 2020).